SPTB (spectrin beta, erythrocytic)
Diseases named in the same sentence as SPTB in open-access papers (continued):
Sharing a sentence is not in itself a finding about the gene and the disease.
Miscarriage (3 papers, 2020 to 2026). A pregnancy that ends at a stage in which the fetus is incapable of surviving on its own, defined as the spontaneous loss of a fetus before the 22th week of pregnancy. "The slightly increased effect on sPTB that our data show for the combined effect of previous miscarriages and TOPs points toward underlying mechanical and biochemical effects of intrauterine procedures that might prevail." (PMID 41557012, 2026). "Null associations with miscarriage, GD, and sPTB were observed." (PMID 38273336, 2024). "Increased levels of PTPRC in the fetal membranes of sPTB indicated activation of T- and B-cell antigen receptor signaling and suggested that sPTB may share a common pathophysiological mechanism with miscarriage." (PMID 32792973, 2020). "We therefore investigated associations between maternal and paternal genetic liability for coronary heart disease (CHD) with APOs (miscarriage, stillbirth, HDP, GD, SGA, LGA, and sPTB)." (PMID 38273336, 2024). "Regarding women: 75,210 for miscarriage, 83,900 for stillbirth, 83,114 for HDP, 83,900 for GD, 66,110 for SGA, 69,789 for LGA, and 83,522 for sPTB." (PMID 38273336, 2024). "Regarding men: 51,156 for miscarriage, 55,790 for stillbirth, 55,273 for HDP, 55,790 for GD, 43,967 for SGA, 46,104 for LGA, and 55,536 for sPTB." (PMID 38273336, 2024).
periodontitis (3 papers, 2023 to 2025). An acute or chronic inflammatory process that affects the tissues that surround and support the teeth. "Chronic inflammatory diseases, such as periodontitis (PD), have been considered SPTB risk factors." (PMID 40943955, 2025). "We propose that assessing the angiogenic vascular status in GCF through liquid biopsies in the first trimester of pregnancy represents a novel and non-invasive approach, furthering our understanding of the association between periodontitis and PTB and of early prediction of sPTB risk." (PMID 40800007, 2025).
placental insufficiency (3 papers, 2024 to 2025). Failure of the placenta to deliver an adequate supply of nutrients and oxygen to the fetus. "An abnormal increase in the sFlt-1/PlGF ratio has been linked with impaired angiogenesis and placental insufficiency, contributing to the pathogenesis of conditions like sPTB and maternal vascular malperfusion." (PMID 38612564, 2024). "Another endocrine pathway which could contribute to a link between placental insufficiency and sPTB is the production of estrogens." (PMID 40497429, 2025).
viral infection (3 papers, 2014 to 2024). "Given the association between infection and sPTB, we would postulate that the underlying cause of raised CVF elafin in women with cervical shortening is the presence of a local subclinical bacteria/viral infection." (PMID 25075964, 2014).
autoimmune disease (2 papers, 2014 to 2025). A disorder resulting from loss of function or tissue destruction of an organ or multiple organs, arising from humoral or cellular immune responses of the individual to their own tissue constituents. "sPTB is associated with rheumatic disease and autoimmune diseases (including neurological and psychiatric diseases), endometriosis and particularly strongly linked with infection (bacterial, parasitic or viral origin)." (PMID 25264875, 2014). "Among the biological correlates, several chronic inflammatory or autoimmune diseases—including PD—have been associated with increased SPTB risk, fostering the widely held notion that these conditions may act as causal risk factors." (PMID 40943955, 2025).
depression (2 papers, 2021). "In this study, we found that concentrations of serum cortisol and scores of ZUNG depression scale were positively associated with the risk of sPTB." (PMID 34557457, 2021). "Pathways associated with PTB and/or sPTB related to cortisol production activation in depression, renal secretion of drugs, transcription role of Vitamin D receptor in regulation of genes involved in osteoporosis, immune responses, and tyrosine metabolism." (PMID 33568690, 2021).
dyslipidemia (2 papers, 2020 to 2025). "Women who were underweight-associated sPTB also showed evidence of dyslipidemia characterized by elevated phospholipids, unsaturated triglycerides, sphingomyelins, cholesteryl esters and long-chain acylcarnitines." (PMID 33201881, 2020). "Women who were obese and had sPTB showed elevated oxidative stress and dyslipidemia characterized by elevated serum free fatty acids." (PMID 33201881, 2020). "Underweight women who experienced sPTB also manifested signs of dyslipidemia but not oxidative stress." (PMID 33201881, 2020).
placental abruption (2 papers, 2016 to 2025). Vaginal bleeding preceding the 20th week of gestation. "sPTB is thought to be the result of multiple aetiologies influenced by a wide number of genetic, biological, psychosocial and environmental factors (e.g. multiple pregnancy, infection, placental abruption and stress) yet the chronology and aetiology of sPTB is insufficiently understood." (PMID 27871275, 2016).
Stillbirth (2 papers, 2024). Death of the fetus in utero after at least 22 weeks of gestation. "Other studies have shown that an antiangiogenic placental state is associated with adverse perinatal outcomes, including sPTB, SGA, and stillbirth, in WHIV on ART." (PMID 39407417, 2024). "However, they were slightly less likely to have experienced stillbirth, GD, SGA, and sPTB." (PMID 38273336, 2024).
abortion (1 paper, 2021). the ending of pregnancy by removing a fetus or embryo before it can survive outside the uterus. "The menstrual pattern is not an independent influencing factor of abortion, sPTB, PROM, LBW, and VLBW (P>0.050)." (PMID 34867783, 2021).
amenorrhea (1 paper, 2021). The absence of menses in a woman who has achieved reproductive age. "The overall incidence of adverse pregnancy outcomes(abortion, sPTB, GDM, HDP, and PROM) was significantly higher in the amenorrhea group than in the regular menstruation and oligomenorrhea groups (25.88% vs. 30.41% vs. 43.69%; P=0.013)." (PMID 34867783, 2021).
atherosclerosis (1 paper, 2014). A disease characterized by the build-up of fatty material and calcium deposition in the arterial wall resulting in partial or complete occlusion of the arterial lumen. "Body mass index (BMI) was associated with both sPTB and PPROM and also two top canonical pathways “Hepatic fibrosis/hepatic stellate cell activation” and “Atherosclerosis Signaling”, although the content of the functions grouped by these categories was different." (PMID 25264875, 2014).
cervical incompetence (1 paper, 2023). A clinical diagnosis presenting with painless cervical dilatation and spontaneous mid-trimester birth in recurrent pregnancies in the absence of spontaneous membrane rupture, bleeding or clinical chorioamnionitis. "In our investigation, we showed the integration of maternal demographic traits and cervical incompetence at mid-gestation into nomograms for estimating individualized risk of sPTB in twin pregnancies." (PMID 38129929, 2023).
COVID-19 (1 paper, 2021). A disease caused by infection with severe acute respiratory syndrome coronavirus 2. "SNVs in SPTB gene were not considered, since they resulted associated both positively and negatively with COVID-19 cases, all with eQTL with positive slopes." (PMID 33981715, 2021).
dilatation (1 paper, 2020). "CS at 6–9 cm and full cervical dilatation did not increase the risk of sPTB < 28 and <32 weeks’ gestation in a subsequent pregnancy." (PMID 33321784, 2020). "Therefore, our hypothesis that increasing cervical dilatation at CS increases the risk of sPTB in a subsequent pregnancy was not supported." (PMID 33321784, 2020).
endothelial dysfunction (1 paper, 2023). In vascular diseases, endothelial dysfunction is a systemic pathological state of the endothelium (the inner lining of blood vessels) and can be broadly defined as an imbalance between vasodilating and vasoconstricting substances produced by (or acting on) the endothelium. "HDP prevalence fluctuates between 5% and 10%, with endothelial dysfunction at the placental level being viewed as a potential sPTB mechanism." (PMID 37790977, 2023).
hydrops fetalis (1 paper, 2021). Hydrops fetalis is a severe and challenging fetal condition usually defined as the excessive accumulation of fetal fluid within the fetal extravascular compartments and body cavities that manifests as edema, pleural and pericardial effusion and ascites. "Herein, we report on a case of neonatal HS caused by a new SPTB gene mutation and characterized by hydrops fetalis." (PMID 33761640, 2021). "Herein, we described a case of neonatal HS caused by a newly discovered SPTB gene mutation characterized by hydrops fetalis and severe postnatal hyperbilirubinemia." (PMID 33761640, 2021). "Thus, we report on a case of neonatal HS caused by a new SPTB gene mutation that was characterized by hydrops fetalis." (PMID 33761640, 2021).
Hyperglycemia (1 paper, 2023). An increased concentration of glucose in the blood. "GDM, characterized by hyperglycemia during pregnancy, has been linked to complications like sPTB." (PMID 37790977, 2023).
intrauterine growth restriction (1 paper, 2019). "These other potential independent variables were identified in bivariate analyses with sPTB <28 gestational weeks (e.g., cervical length, laser time, GA at surgery, Quintero stage, and donor intrauterine growth restriction)." (PMID 30872799, 2019).
ischemic stroke (1 paper, 2024). A stroke disorder caused by obstruction of blood flow to the brain, due to thrombotic (local blood clot formation) or embolic (due to a blood clot or other material traveling from another site) event. "DEPs, including GNAQ (G protein subunit α Q), CA3 (carbonic anhydrase 3), ARL6IP5 (ADP ribosylation factor like GTPase 6 interacting protein 5), and SPTB (spectrin β) were identified in total participants between recurrence and nonrecurrence patients with ischemic stroke." (PMID 38420847, 2024).
lung adenocarcinoma (1 paper, 2016). A carcinoma that arises from the lung and is characterized by the presence of malignant glandular epithelial cells. "Of the 16 distinguishing proteins, 8 were significantly elevated in lung adenocarcinoma (COPG1, STOML2, HYOU1, PDIA4, EPRS, APEX1, LRPPRC and NANS) whereas 8 proteins were significantly decreased in lung adenocarcinoma (SPTB, SPTA1, ANK1, SLC4A1, HBG1 and HBG2)." (PMID 27799870, 2016).
lung disease (1 paper, 2019). "The association of several oxidative stress-associated processes and sPTB have been previously reported, and oxidative stress has been associated with elevated alkane levels in gastroenteric disease, lung disease, and other chronic diseases of metabolism." (PMID 31548567, 2019).
macrosomia (1 paper, 2021). "The degree of increased blood glucose in pregnant women is significantly related to the increased risk of macrosomia, sPTB, HDP, and PROM." (PMID 34867783, 2021).
meningioma (1 paper, 2020). A generally slow growing tumor attached to the dura mater. "This study revealed the identification of phosphorylated sites of several proteins that were found to play a role in meningioma pathobiology by several studies including EPB41L2, NDRG2, SPTB, MAGED2, MXRA7, and nearly 51 Kinases which were also mapped further through Kinome Analysis." (PMID 32974197, 2020).
metastatic cancer (1 paper, 2016). A carcinoma which has spread from the original site of growth to another anatomic site. "Adenocarcinoma-associated reductions in spectrins, SPTB and SPTA1, and ankrin (ANK1) all interact with each another to regulate cell shape and membrane integrity, so paralleled changes likely reflect changes in cell adherence, which is a known hallmark of metastatic cancer." (PMID 27799870, 2016).
Neonatal sepsis (1 paper, 2024). Systemic inflammatory response to infection in newborn babies. "Tregs have been implicated in conditions affiliated with sPTB such as neonatal sepsis, necrotising enterocolitis, and others, where their level of functionality has been proposed to contribute to dysregulated immune response and long-term effects on neonatal health." (PMID 39595948, 2024).
obstetric disorder (1 paper, 2026). Disorder associated with pregnancy, childbirth, and puerperium. "Neither do we have either an effective first-trimester screen for sPTB nor a dual screen for both of these major obstetric disorders." (PMID 41827937, 2026).
periodontal disease (1 paper, 2025). "This study aimed to evaluate the association between gingival crevicular fluid (GCF) levels of placental growth factor (PlGF) and soluble fms-like tyrosine kinase-1 (sFlt-1) and sPTB risk and to assess their correlation with periodontal disease severity during early pregnancy." (PMID 40800007, 2025).
periventricular leukomalacia (1 paper, 2024). Periventricular leukomalacia (PVL) is a brain injury disorder characterized by the death of the white matter of the brain due to softening of the brain tissue. "Inflammatory cytokines associated with the onset of sPTB itself are also thought to further contribute to neonatal brain injury such as IVH and white matter injury including punctate lesions and periventricular leukomalacia." (PMID 38126921, 2024).
plasma cell leukemia (1 paper, 2022). An aggressive plasma cell neoplasm characterized by the presence of neoplastic plasma cells in the peripheral blood. "It is interesting to note that two other MAPK pathway-enriched genes, SPTB and PTK2/FAK1, also play a role in the development of an aggressive and rare form of EMM called plasma cell leukemia." (PMID 36611892, 2022).
polycythemia (1 paper, 2023). Abnormally high mass or concentration of red blood cells in the blood, either due to an increase in erythropoiesis or a decrease in plasma volume. "Of note, the deficiency or mutation of the genes such as EPB42, SPTB and SPTA1 can cause hereditary polycythemia, 25], which is also an important cause of hemolytic anemia." (PMID 37507679, 2023).
pregnancy disorder (1 paper, 2022). A disorder that is related to pregnancy. "The successful identification of a predictive test for both sPTB and EOP would provide caregivers a single test that could identify asymptomatic women likely to develop one or more of the three most important pregnancy disorders, two which already have therapeutic options that may improve outcome." (PMID 35741140, 2022).
Premature rupture of membranes (1 paper, 2026). Premature rupture of membranes (PROM) is a condition which occurs in pregnancy when the amniotic sac ruptures more than an hour before the onset of labor. "We now have preventative therapies for women at high risk for EOP with delivery at <33 wks' gestation (aspirin) and sPTB at ≤33 wks' gestation (+/- preterm premature rupture of membranes (PPROMs)) (docosahexaenoic acid (DHA)." (PMID 41827937, 2026).
protein deficiency (1 paper, 2023). "Previous research has shown that erythrocyte membrane protein deficiency caused by pathogenic mutations in the ANK1, SLC4A1, SPTA1, SPTB, and EPB42 genes is the molecular pathogenesis of HS." (PMID 36647015, 2023).
thalassemia (1 paper, 2024). An inherited blood disorder characterized by a decreased synthesis of one of the polypeptide chains that form hemoglobin. "In our study, we found overexpression of the genes SLC4A1, ANK1, EPB41, EPB42, SPTA1, SPTB, and STOM, all of which are involved in maintaining erythrocyte structure and function, in patients with thalassemia and SCD." (PMID 39519257, 2024).
vitamin D insufficiency (1 paper, 2020). "At 10–18 weeks of gestation, 146 differentially expressed genes (25 upregulated) were associated with both vitamin D insufficiency and sPTB in the discovery cohort (FDR < 0.05)." (PMID 31995561, 2020).
infection (19 papers, 2014 to 2025). The state of being infected such as from the introduction of a foreign agent such as serum, vaccine, antigenic substance or organism. "This overgrowth can outweigh the beneficial microbiota, subsequently increasing the risk of infection (e.g. BV) and sPTB." (PMID 38196946, 2023). "Taken together, our observations lend credence to a possible association between female genital tract colonisation by anaerobic bacteria, and infection/inflammation-associated sPTB." (PMID 29367099, 2018). "Infection is the principle pathologic process with an established causal link to sPTB and a defined molecular pathophysiology." (PMID 25965269, 2015). "sPTB is closely linked with underlying inflammation and infection, and there has been considerable focus on the potential of inflammatory cytokines as predictive biomarkers." (PMID 25075964, 2014). "Inflammation/infection has been implicated in the aetiology of sPTB itself." (PMID 38126921, 2024). "About 35% of sPTB cases are associated with infections and inflammation." (PMID 38196946, 2023). "The direct causes of sPTB are often unknown, but overt infection leading to inflammation and immune activation are common antecedents." (PMID 35595739, 2022). "High elafin could be protective against sPTB, limiting damage to host tissues by neutrophil activity by inhibiting neutrophil elastase and protease 323, counteracting ascending infection and the associated cervical degradation and inflammation." (PMID 32694552, 2020). "Also, most women (84.8%) in our study were considered late preterm and although we cannot address this question, it is possible that sPTB driven by an ascending infection would be more evident in a high-risk cohort or extreme preterm cases." (PMID 29954448, 2018). "The hormone-regulatory component of the sPTB gene group network connects all other sPTB-associated functions in the network, indicating that this may be crucial for the upstream pathways such as the infection/inflammation pathway." (PMID 25264875, 2014). "The current findings demonstrated that blood inflammation- and infection-related parameters, such as white blood cell and monocyte counts, changed significantly during pregnancy in women with sPTB." (PMID 40958265, 2025). "The aetiology of sPTB is complex and likely multi‐factorial but infection/inflammation is thought to play a significant role, particularly at early gestations." (PMID 38126921, 2024). "The most densely connected to sPTB is the inflammatory/infection related network that can be present upstream as well as downstream of associated hormonal perturbations." (PMID 25264875, 2014). "Differentially expressed lncRNAs that were identified from the human placentas of sPTB and PPROM may regulate their associated mRNAs through differential mechanisms and connect the ubiquitin-proteasome system with infection-inflammation pathways." (PMID 25884766, 2015). "In the setting of sPTB, it is the association with inflammation rather than culture-proven infection that correlates with both adverse outcomes and pathology." (PMID 25965269, 2015). "In conclusion, the current findings demonstrated that blood inflammation- and infection-related parameters, such as WBC count and monocyte count, changed significantly during pregnancy in women with sPTB." (PMID 40958265, 2025). "Thus, bacterial endotoxin LPS used in vitro is an experimental tool to mimic infection-induced myometrial inflammation and to examine the underlining mechanism of BSCI action; it does not necessarily recapitulate the full spectrum of inflammatory stimuli underlying the initiation of sPTB." (PMID 35011690, 2021). "Our finding that transcription of mRNA of STAM may be regulated by lncRNA opens a new approach to study the pathogenesis of sPTB and PPROM through the connection between UPS and infection-inflammation pathways." (PMID 25884766, 2015).
infection (continued). "However, what is understood is that this rupture of membranes is strongly associated with infection and an inflammatory environment, showing that sPTB cases with pPROM have increased rates of infection/inflammation when compared to sPTB without pPROM." (PMID 39595948, 2024).